RN7SL601P (RNA, 7SL, cytoplasmic 601, pseudogene)
Gene: Miscellaneous RNA gene on chromosome 17 (11,157,455 to 11,157,747, forward strand). Ensembl gene ENSG00000243346.
Homologues: Orthologues: chimpanzee Metazoa_SRP (98% identical). Paralogues in human: RN7SL2 (75% identical), RN7SL218P (75% identical), RN7SL1 (75% identical), RN7SL296P (75% identical), RN7SL301P (75% identical), RN7SL660P (74% identical), RN7SL482P (74% identical), RN7SL126P (74% identical), RN7SL326P (74% identical), RN7SL357P (74% identical), RN7SL3 (73% identical), RN7SL493P (73% identical), and 699 more.